ARG1 (arginase 1)
Diseases named in the same sentence as ARG1 in open-access papers (continued):
Sharing a sentence is not in itself a finding about the gene and the disease.
tumor (continued). "Furthermore, treatment with miR‐142‐5p‐EVs and miR‐183‐5p‐EVs increased the expression of arginase 1 (ARG‐1), a well‐known M2 marker, in the 4T1 tumours (P < 0.05, P < 0.01, respectively)." (PMID 35656866, 2022). "Both PL-TLs and LLC-TLs were able to induce Arg1 mRNA in naive HDNs, demonstrating that this process is not tumor model specific." (PMID 36377658, 2022). "Our results showed that 1.0 g/kg BJIKT administration dramatically decreased the ARG-1 expression in tumor-infiltrating MDSCs, but not significantly in NOS2 expression." (PMID 35873573, 2022). "The levels of iNOS and Arg-1 showed no significant change in MDSCs from WT and FcγRIIB-KO tumor-bearing mice." (PMID 34976216, 2022). "Next, to determine whether CCR2 was expressed in MDSCs, we performed multicolor immunofluorescence staining for CCR2, Arg1, GR1, and CD11b in the tumor/stromal coxenografts." (PMID 34874922, 2022). "Tumor malignant phenotype related IGFBP2 and KRT18 were significantly enriched in KRAS-Mut subtype, whereas neutrophils and macrophages related CD177, MMP1 and ARG1 were enriched in WT subtypes." (PMID 35836817, 2022). "The function of T cells is dependent on their interaction with tumour cells and other TME cells, thereby, the factors influencing its activation include (apart from metabolic factors) TGF-β, IL-10 and ROS (by TAMs); Arg1, iNOS and ROS (by MDSCs); PD-L1 or CD80 receptors expression (in tumour cells)." (PMID 35406451, 2022). "Tumor-derived succinate also promotes succinate receptor 1 (SUCNR1)/phosphoinositide 3-kinase (PI3K)/HIF-1α-dependent polarization of peritoneal macrophages in vitro, enhancing macrophage expression of arginase-1." (PMID 34876704, 2022). "Since M2-like macrophage that showed high expression of Arg-1 was one of the major immunosuppressive cell types in PDAC, we thus combined a small molecule compound Arg-1 inhibitor (PubChem CID 66833213) with anti-PD-1 antibody to treat KPC and PancO2 tumor-bearing mice." (PMID 35316682, 2022). "Similarly, HDNs activated by PL or LLC tumor lysates (TLs) also reduced IFN-γ secretion by CD8+ cells, suggesting that a TME factor is responsible for neutrophilic ARG1 expression in this context." (PMID 36377658, 2022). "In this research, it was found that a reduction of MDSC in tumor tissues, in which IBC could allow for improved tumor progression via inhibiting the mRNA expression of ARG1 and TGF-β." (PMID 36091768, 2022). "Reanalysis of the ARG1-FISH data and spatial plots showed that ARG1-FISH+ cells were also preferentially located within the tumor compartment as opposed to outside of it, placing ANXA2 protein and ARG1 transcript in a similar anatomical location." (PMID 36377658, 2022). "The inhibition of COX-2/ PGE2 signaling could suppress MDSC functions, which leads to impairing the production of Arg-1 and ROS, improves CD8+ T cytotoxicity, and delays tumor growth." (PMID 36246629, 2022). "Indeed, PPARβ/δ is known to induce immunosuppressive and proangiogenic gene expression (such as IL-10, Arg1 and VEGF), generating tumor escape and progression." (PMID 35406621, 2022). "In tumor specimens from non-responders, however, the presence of arginase-1 expressing macrophages adjacent to B and T cells is associated with lack of response." (PMID 35634309, 2022). "SEMA3C modified the PD-L1 expression in tumor and immune cells and is correlated with the M2-like macrophage marker ARG1/CD163 expression, which could reshape the tumor microenvironment." (PMID 35785187, 2022). "We found that bacteria-positive tumours showed reduced expression levels of CD4 and CD8, along with an increased expression of immunosuppressive molecules such as CTLA4 and ARG1, and an enrichment of CD66b+ myeloid cells, supporting previous bulk tissue analysis." (PMID 36385528, 2022). "In addition, macrophages inhibit the anti-tumor effect of CD4 + T cells, and inhibit T cell proliferation by secreting several molecules like TGF-β and Arg-1." (PMID 35246045, 2022).
tumor (continued). "Besides, the expression of IL-6 and TNF-α were upregulated while the expression of IL-10, CCL22, Arg-1 and CD206 were downregulated in the tumor tissues from ACEA-treated group." (PMID 35641479, 2022). "In addition, tumor-resident MDSCs produce cyclo-oxygenase 2 (COX-2), arginase 1 (ARG1), inducible NO synthase (iNOS), IL-10, and indoleamine 2,3-dioxygenase (IDO), which accentuate the suppressor milieu." (PMID 36072935, 2022). "The growing number of arginase-1 generated by MDSCs depletes L-arginine, leading to the G0–G1 phase being blocked during T cell proliferation and the low expression of the CD3ζ chain of the TCR, connected with tumor escape in vivo." (PMID 35053426, 2022). "ARG1-targeting therapeutic vaccines changed the cell composition of the TME, resulting in increased T cell infiltration and a change in the M1/M2 ratio of tumor-infiltrating macrophages." (PMID 36330525, 2022). "In contrast, Arg1+Iba1+ TAM2s were downregulated in TNBC tumor after treatment with p40 mAb, but not control IgG, suggesting that p40 mAb immunotherapy is capable of switching TAM2 to TAM1 in TNBC tumor." (PMID 35053375, 2022). "The level of ARG-1 is reduced in CD8+ T cells, thereby enhancing their anti-tumor activity." (PMID 35889289, 2022). "At 0 h and 1, 4, 7,14, and 21 days after the tumor was resected, the animals were sacrificed, and the brain tissues from the area of resection were analyzed by Western blot to identify the expression levels of myeloid cell markers Iba1, CD86 and Arg1." (PMID 35884700, 2022). "Immunohistochemically, the tumor cells were negative for Arg-1, glypican-3 (GPC3), hepatocyte specific antigen (HSA), epithelial membrane antigen (EMA), CK7, CK19, desmin, HMB45, and chromogranin A (CgA)." (PMID 34218806, 2021). "Here, we detected non-macrophage ARG1 expressing populations in higher numbers in both tumor parenchyma and stroma of HPV− tumors." (PMID 33807310, 2021). "The result of IHC suggested inhibition of CXCR2 could decrease neutrophil infiltration and attenuate immunosuppression in tumor microenvironment with decreased levels of TGF-β and Arg-1." (PMID 33814009, 2021). "With the continuous exploration of emerging immune checkpoints, TIM3, ARG1, and EBAG9 have been confirmed to exist in exosomes and may be involved in the regulation of tumor progression." (PMID 34743730, 2021). "When analyzing 3D co-cultures with BMDMs cultured with only one other cell type (i.e., with fibroblasts or tumor cells), we found that it was the fibroblasts that favored the M0 BMDM transition, observing a larger fraction positive for Arg-1 by day 7 (19% vs. 13%)." (PMID 34572807, 2021). "In addition, M2 also inhibit T cells activity by the depletion of L-arginine that is required for T cells function in the TME through secreting arginase 1 (ARG1), an enzyme characteristically expressed in M2 to promote tumor growth and progression." (PMID 34625124, 2021). "This was paralleled with a significant reduction of pro-tumor M2-like CD206+ and Arg1+ TAMs." (PMID 34446712, 2021). "The data herein suggest that their expression alone does not blunt the development of CRC, indicating that the reduction in average tumor size seen in M(IL4)-treated mice is likely not dependent on arginase-1, FIZZ1 or Ym1." (PMID 34691050, 2021). "The result was also confirmed on IL-4-stimulated microglial cells: BV2-derived sEVs were not able to modify the expression of pro-tumor genes (Arg-1, Cd163, Cd206, Fizz-1, and Ym1), with all of them upregulated by IL-4 treatment compared to the control cells." (PMID 34440835, 2021). "ARG1 inhibitors (such as CB-1158) showed encouraging preclinical results, increasing tumor-infiltrating NK cells and CD8+ T cells, reducing tumor burden, and decreasing MDSCs recruitment into the TME." (PMID 34025641, 2021).
tumor (continued). "f (one TCM herb), was found to inhibit the expression of CD206, arginase 1, and CD204, and inhibit the secretion of anti-inflammatory cytokines, further inducing the decreased number of tumor-related M2 polarized macrophages to block tumor angiogenesis." (PMID 33748122, 2021). "In this study, we detected ARG1 expression and higher pathological stage of the tumor as a negative prognostic factor for overall survival in patients with head and neck tumors." (PMID 33807310, 2021). "However, M2 macrophages release a great number of immunosuppressive cytokines such as arginase 1 (ARG1), TGF‐β, and IL‐10 to promote immunosuppression, tumor progression, and contribute to resistance to chemotherapies." (PMID 34390203, 2021). "The pharmaceutical targeting of MDSC end products iNOS or arginase 1, or systemic treatment with a phosphodiesterase V (PDE5) inhibitor, suppressed MDSC accumulation and function in HCC, reinstating an important role for NK cells in anti-tumor immunity." (PMID 34445750, 2021). "CB-1158, an arginase 1 inhibitor synthesized at Calithera Biosciences blocked myeloid cell-mediated suppression of T cell proliferation in vitro and reduced tumor growth in several mouse models of non-CNS tumors (CT26, LLC, B16, and 4T1 tumors)." (PMID 34504786, 2021). "TAMs are also broken down into subsets based on polarization to the M1 macrophage-like phenotype (pro-inflammatory/anti-tumor) CD68+ CD80/86+ CD11c+ iNOS+ and the M2 macrophage-like phenotype (pro-tumor) CD163+ CD204+ CD206+ Arg1+, with M2-like TAMs being the most immunosuppressive." (PMID 34136405, 2021). "An increased level of ARG1 mRNA and higher tumor stage were found as negative prognostic factors of patients with HNSCC." (PMID 33807310, 2021). "PD-L1, CTLA-4, TIM3, ARG1, and EBAG9 have been confirmed to exist in exosomes and may be involved in the regulation of tumor progression." (PMID 34743730, 2021). "In contrast, M2-like cells not only produce tumor growth factors such as IL-6 but also produce angiogenic molecules, including VEGF and immunosuppressive factors such as arginase 1 (Arg1), IL-10, TGF-β, and indoleamine 2,3-dioxygenase (IDO), resulting in tumor promotion." (PMID 34071550, 2021). "In line with this, the expression of ARG1 in the TME may limit the availability of arginine, which can inhibit the anti-tumor response of NK cells and T cells." (PMID 33514004, 2021). "Anti-tumor neutrophils are characterized by high ROS production together with TRAIL, while pro-tumor neutrophils produce ROS together with nitric oxide radicals, ARG1 and IDO." (PMID 34572138, 2021). "Immunohistochemically, tumor cells were negative for Arg-1, glypican-3 (GPC3), hepatocyte specific antigen (HSA), and positive for synaptophysin (Syn), α-inhibin, and Melan A. The Ki-67 index was 1 %." (PMID 34218806, 2021). "M2-type macrophages are featured by arginase 1 (Arg1), CD206, IL-10, and TGF-β, which may facilitate tumor progression." (PMID 32391256, 2020). "Arginases may act intracellularly (cytoplasmic ARG1 and mitochondrial ARG2) and extracellularly (secreted ARG1) leading to the local depletion of L-arginine in tumor microenvironment." (PMID 33986723, 2020). "In this case, the MHCs class I would carry viral antigens ready to be recognized, but due to the immune escape activated by the tumor cells, with the production of ARG1, LAG3, and CTLA4, they do not recognize it." (PMID 32331228, 2020). "Additionally, myeloid-derived suppressor cells (MDSCs) enhance stemness and promote metastasis, induce resistance to therapy, and limit the anti-tumor functions of T cells through MDSC signature molecules, nitric oxide (NO), and arginase-1 (Arg-1)." (PMID 33182298, 2020). "Furthermore, these Gr1+ cells exhibited marked enrichment for suppressive myeloid genes, including Arg1, INOS, NOX2, and S100A8, compared with initial tumor dissociates or Gr1-depleted dissociates." (PMID 32634121, 2020).
tumor (continued). "It was also associated with a tendency towards a higher expression of ARG1 and DDAH1 in noncancerous tumor-adjacent tissue." (PMID 32872669, 2020). "In that study, MDSCs induced tumor-specific Tregs via antigen uptake, processing, and presentation, which requires ARG1 but not TGF-β." (PMID 32793192, 2020). "Single immune cells were detected with trained algorithms in annotated tumor, invasive margin and normal colon ROI and cell densities of CD11b+CD14+, CD11b+CD15+ and ARG1+ myeloid cells, and CD8+Ki67+/–, CD8+Ki67+/– and FOXP3+ T cells were computed respectively." (PMID 33193316, 2020). "Nitric oxide synthase, arginase 1 and matrix metalloproteinase-9 released by neutrophils activate the immune escape mechanism whilst inhibiting the anti-tumor properties of CD8+ T lymphocytes, which ultimately results in tumor metastasis." (PMID 33120809, 2020). "Of note, HIF1 transcription has also been shown to activate multiple anti-inflammatory pathways such as the expression of arginase 1 and VEGF in M2-like tumor-infiltrating macrophages and the upregulation of A2B adenosine receptor promoting Th2 and Treg differentiation." (PMID 33257753, 2020). "Moreover, phenformin, in combination with anti-PD-1 administration, reduced the immunosuppressive expression of ARG1 by MDSCs, resulting in a synergistic effect in the induction of CD8+ T cells’ infiltration in TME and reduced tumor growth." (PMID 32823961, 2020). "Conversely, the efficacy of CB-1158 in reducing tumor volume was limited after depletion of either CD8+ or NK cells, thus indicating that certain immune cell populations are required for the full anti-tumor activity of the ARG-1 inhibitor in this cancer model." (PMID 33212945, 2020). "Alternatively activated M2 macrophages regulate anti-inflammation and reduce NO and reactive oxygen species (ROS) levels but induce Arginase-1, anti-inflammatory cytokines (such as TGF-β, IL-10 and IL-6) and growth factors that support neoplasia and induce tumor cell movement." (PMID 32059469, 2020). "A TAN-related cell population, PMN–MDSCs were increased in tumor sites and peripheral blood of several types of cancers including human NSCLC, PDAC and glioma and can in vitro suppress T cell functions with the use of Arg-1." (PMID 32422991, 2020). "Besides, QRHX intervention can reduce the infiltration of TAMs in tumor tissues of lung cancer mice, reduce the expression of IL-6, TNF-α, ARG-1, CD31, and VEGF, and increase the expression of inducible NO synthase (iNOS)." (PMID 33224886, 2020). "IL-17 not only enhances tumor-infiltrating MDSCs, probably by increasing CXCL1 and CXCL5 secretion by tumor cells, but also potentiates their inhibition on T cells through upregulation of ARG1 and IDO." (PMID 32793192, 2020). "In addition, the protective function of dendritic cells in stimulating the anti-tumor response is blunted by tumor factors that inhibit dendritic cell maturation and function such as PD-1 expression and release of IL-10, TGF-β1, arginase-1, and IDO." (PMID 33371456, 2020). "Previous studies found no ARG1 expression in LLC tumor cell in vitro, or from the cyto-spins, and most of the expression was in the myeloid cells." (PMID 30728077, 2019). "We further evaluated the functional markers of macrophages and found that infiltration of arginase-1+ M2-like TAMs decreased in the mPanIN/PDAC lesions, whereas iNOS+ M1-like TAMs increased in the tumor area, resulting in a significant induction of apoptosis of the tumor cells." (PMID 30659170, 2019). "In addition, arginase 1 (ARG1) is upregulated by TAMs and tumor cells, and its expression inhibits T cell activation by reducing arginine entry into tumor‐infiltrating immune cells." (PMID 31365790, 2019).
tumor (continued). "Accordingly, pharmacological blockade of C5aR1 in a syngeneic model of lung cancer impaired tumor growth, decreased the percentage of splenic MDSCs, and downregulated immunosuppression-related genes including ARG1, IL6, IL10, CTLA4, LAG3, and PDL1 within the tumor milieu." (PMID 31001273, 2019). "Because both ARG1 and IDO1 act as immune checkpoint mechanisms in neoplasia, their functional “alliance” in specific immune cells could be remarkably effective in controlling adaptive immunity toward auto-antigens." (PMID 31354721, 2019). "Further, up-regulation of fatty-acid synthase (FASN) by M-CSF in tumor infiltrating myeloid cells was required for PPARβ/δ-dependent expression of immunosuppressive and pro-angiogenic genes (e.g. IL-10, Arg1 and VEGF) and consequent promotion of tumor progression, in a model of Lewis lung cancer." (PMID 31535085, 2019). "The expression of ARG1, iNOS, and NOX2 was significantly increased in tumor-infiltrated MDSCs." (PMID 31129755, 2019). "Three cycles of the co-cultivation of cancer and monocytic cells led to the secretion of several cytokines typical of the tumor microenvironment (TME) and to pro-cancer activation of the monocytes/macrophages as established by elevation of F4/80 and arginase-1 markers." (PMID 31861801, 2019). "The expression of the M2 macrophage marker Arginase-1 in the liver was not affected by the tumor or the treatments." (PMID 31731747, 2019). "Additionally, GS ablation in TAMs reduces M2 markers, such as ARG1 and CD206, and decreases tumor metastasis in mice." (PMID 31333642, 2019). "MDSCs produce high levels of suppressive molecules, such as Arg1, reactive oxygen species (ROS), inducible nitric oxide synthase (iNOS), and prostaglandin E2 (PGE2), to directly suppress effector T cell–induced anti-tumor immune response." (PMID 31438991, 2019). "The tumor lesions exhibited cellular atypia with large nuclear, trabecular structures, and fatty changes and showed immunoreactivity for GS, GPC3, HSP70, and ARG1." (PMID 31238892, 2019). "Lactic acid secreted by cancer cells can induce the expression of the vascular endothelial growth factor (VEGF) in macrophages and the expression of Arg1 and CD206 (a major M2 phenotype marker of macrophages), which promotes tumor growth by inducing neovascularization." (PMID 31324019, 2019). "Given that arginase 2 mRNA was expressed in the healthy tissue and not specifically elevated in the tumor both in our mice and patient tumors, we focused on characterizing arginase 1 expression in CD66b or CXCR2 expressing myeloid cells in the patient tissues." (PMID 30728077, 2019). "The authors showed that the tumor-cell-conditioned medium increased the percentage of M2 macrophages determined via RT-PCR and upregulated M2 polarization markers CD163, CD206, IL-10, and Arg1 while downregulating M1 marker TNFα." (PMID 31921102, 2019). "Strikingly, a recent paper reported that bone marrow (BM)-derived MDSCs require direct cell-cell contact rather than Arg1 expression or production of soluble factors to mediate immunosuppression in different tumor models (e." (PMID 31130949, 2019). "Moreover, it was shown that tumor-conditioned media or lactic acid up-regulated the expression of VEGF angiogenic factor and Arg-1 M2 phenotype marker in macrophages." (PMID 31324019, 2019). "Since parental ID8 tumor cells do not express ARG1, we overexpressed V5-tagged murine ARG1 (ID8-ARG1-V5) using lentiviral transduction system." (PMID 31278254, 2019). "Tumor-derived lactate drives macrophage polarization toward a tumor-promoting phenotype in mice, where HIF-1α-dependent lactate-induced expression of arginase 1 and VEGF might also contribute to immunosuppression and tumor evasion." (PMID 31781212, 2019). "Other BAL neutrophil genes, such as IL17, S100a9, S100a8 and Arginase 1 were not statistic altered by the tumor growth." (PMID 31712726, 2019).